MMP7 (matrix metallopeptidase 7)
Diseases named in the same sentence as MMP7 in open-access papers (continued):
Sharing a sentence is not in itself a finding about the gene and the disease.
myeloma (continued). "The present study identifies an unexpected role for MMP-7 in myeloma pathogenesis, with a striking increase in myeloma tumor burden and osteolytic bone disease in myeloma-bearing MMP-7 deficient mice, as compared to wild-type controls." (PMID 28241871, 2017). "Interestingly, they found an increase in myeloma cell viability by co-culturing with 2T3 pre-osteoblasts, whereas overexpression of MMP-7 in pre-osteoblasts suppressed this phenomenon." (PMID 37823051, 2023). "In contrast, the role of MMP-7 is relatively unknown in myeloma, and is currently limited to the expression of MMP-7 by human myeloma cells, with resultant in vitro activation of MMP-2." (PMID 28241871, 2017). "However, cleavage of these substrates would be predicted to decrease their anti-tumor effect, rendering them unlikely candidates to explain the anti-myeloma effect of MMP-7 in the present study." (PMID 28241871, 2017). "In vitro studies suggest that myeloma-derived MMP-7 can activate stromal MMP-2, however the in vivo role of MMP-7 in myeloma pathogenesis thus far is unknown." (PMID 28241871, 2017). "An increase in the endogenous MMP inhibitor TIMP-1 was detected in patients with multiple myeloma, which may account for the reduction in MMP-7 activity, although it is likely that other mechanisms also contribute." (PMID 28241871, 2017). "Accompanying the increase in tumor burden, myeloma-bearing MMP-7−/− mice developed a more severe osteolytic bone disease, with decreased trabecular bone volume and an increase in osteolytic lesions as compared with myeloma-bearing WT mice." (PMID 28241871, 2017). "In order to determine whether the role of MMP-7 in murine myeloma pathogenesis translated to the clinical setting, we measured the concentration and activity of MMP-7 in newly diagnosed multiple myeloma patients." (PMID 28241871, 2017). "Since MMP-7 activity is decreased in myeloma in vivo, both in patients with multiple myeloma and in a murine model of myeloma, we sought to determine whether the endogenous MMP inhibitors were elevated in these samples." (PMID 28241871, 2017). "This review focuses on the role of MMP-1, MMP-2, MMP-7, MMP-9, MMP-13, MMP-14, and MMP-15 and the four types of TIMPs in the invasion of myeloma cells, angiogenesis, osteolytic osteopathy, to offer some novel perspectives on the clinical diagnostics and therapeutics of MM." (PMID 37823051, 2023). "This suggests that the myeloma-suppressive effect of MMP-7 is not merely a direct anti-tumour effect, but likely a complex mechanism involving cleavage of multiple substrates within the tumour-bone microenvironment." (PMID 28241871, 2017). "Further support for a role for MMP-7 in myeloma pathogenesis was provided by a significant reduction in MMP-7 activity in serum of myeloma-bearing mice as compared to non-tumor controls." (PMID 28241871, 2017).
nasopharyngeal carcinoma (3 papers, 2019 to 2022). A carcinoma arising from the nasopharyngeal epithelium. "Other reports have demonstrated that MTA2 overexpression could activate AKT and upregulate MMP-7 expression in nasopharyngeal carcinoma cells." (PMID 31771219, 2019).
oesophageal cancer (3 papers, 2003 to 2022). "The upregulated expressions of MMP1 and MMP7 with miR-330-5p silencing were of particular interest because MMP1 and MMP7 have previously been reported as prognostic markers in oesophageal cancer." (PMID 31391080, 2019). "The rate of MMP-7 expression was a little low, 23.6% of 55 patients, because we examined only superficial oesophageal cancer." (PMID 14647147, 2003). "There have been some reports on MMP-7 in oesophageal cancer." (PMID 14647147, 2003). "At the invasive front of oesophageal cancer, MMP-7 may have an important role in invasion and metastasis." (PMID 14647147, 2003). "To determine the appropriate treatment for superficial oesophageal carcinoma, we retrospectively studied expression of MMP-7 and MMP-9 and investigated clinical pathological factors and outcomes in superficial oesophageal cancer treated by endoscopic and surgical resection." (PMID 14647147, 2003). "Although it had no relation with minute changes like lymphatic permeation, coexpression of MMP-7 and MMP-9 may suggest nodal metastasis in oesophageal cancer." (PMID 14647147, 2003). "The combined expression of MMP-7 and MMP-9 may be a good marker for the degree of malignancy of oesophageal cancer and for the presence of lymphatic metastasis." (PMID 14647147, 2003). "In conclusion, combined MMP-7 and MMP-9 expression may be a good marker for the malignancy level of oesophageal cancer and for the presence of lymphatic metastasis, not venous invasion." (PMID 14647147, 2003).
osteoarthritis (3 papers, 2012 to 2020). A noninflammatory degenerative joint disease occurring chiefly in older persons, characterized by degeneration of the articular cartilage, hypertrophy of bone at the margins and changes in the synovial membrane. "The mRNA expression of catabolic factors MMP-3, MMP-7, and MMP-13 was significantly decreased in rat in the FJH-KO100 and FJH-KO150 groups compared with that in rats with MIA induced osteoarthritis (p < 0.05)." (PMID 33233504, 2020).
preeclampsia (3 papers, 2017 to 2022). Preeclampsia is a hypertensive disorder of pregnancy that is characterized by new-onset hypertension with proteinuria presenting after 20 weeks of gestation, and depending on mild or severe forms may initially present with severe headache, visual disturbances, and hyperreflexia. "There is also histological evidence to support the involvement of MMP-7 in the processes associated with the development of preeclampsia and early preeclampsia." (PMID 31163045, 2019). "In atherosclerotic plaques, MMP-7 is expressed by lipid-laden macrophages, the same cells present in acute atherosis of the spiral arteries, a lesion associated with preeclampsia." (PMID 28738067, 2017). "Collectively, these reports suggest that MMP-7 may be involved in two fundamental processes associated with the development of preeclampsia: placentation and inflammation." (PMID 28738067, 2017). "MMP-7 may also be involved in processes leading to the formation of atherosclerotic plaques that show characteristics (e.g., lipid-laden macrophages) similar to acute atherosis of the spiral arteries associated with preeclampsia." (PMID 31163045, 2019). "Until 22.1 weeks, MMP-7 has the highest predictive performance for the identification of patients at risk to develop late-onset preeclampsia regrades to severity, whereas, after 22 weeks, the set of optimal proteomic predictors differs according to the severity of late-onset preeclampsia." (PMID 28738067, 2017). "Additionally, MMP-7 can act as a sheddase for syndecan-1, a major transmembrane heparan sulfate proteoglycan expressed on the surface (glycocalyx) of epithelial, endothelial, and syncytiotrophoblast cells, which are implicated in the pathophysiology of preeclampsia." (PMID 31163045, 2019). "Our current report observing that an increased maternal plasma abundance of MMP-7 and gpIIbIIIa is predictive of early preeclampsia during the first half of pregnancy is novel." (PMID 31163045, 2019). "At 16.1–22 weeks of gestation, more than two-thirds of patients who subsequently develop early preeclampsia can be identified by an elevated MMP-7 and gpIIbIIIa in maternal plasma (10% FPR)." (PMID 31163045, 2019). "A possible explanation for the increased maternal plasma MMP-7 in preeclampsia is that it is a marker of abnormal placentation." (PMID 31163045, 2019). "At 16.1–22 weeks of gestation, MMP-7 was again the single best predictor of late-onset preeclampsia with a sensitivity of 68% at a FPR of 20%, and 62% at a FPR of 10% (AUC = 0.83; 0.82 bootstrap estimate)." (PMID 28738067, 2017). "Until 22 weeks of gestation, MMP-7 was the most predictive protein for the development of late-onset preeclampsia, either in mild or severe form." (PMID 28738067, 2017). "Elevated abundance of MMP-7 in maternal plasma before 22 weeks of gestation was the strongest predictor of late-onset preeclampsia." (PMID 28738067, 2017). "The frequency of the MMP7 −181G allele was not significantly different between the groups with severe and mild preeclampsia as well as the healthy pregnant group." (PMID 35885543, 2022). "This study did not reveal a direct influence of MMP7 −181A>G polymorphism on the risk of preeclampsia." (PMID 35885543, 2022). "Recent evidence suggests that MMP-7 may play a role in atherosclerotic disease, which has many parallels to preeclampsia." (PMID 28738067, 2017). "Of note in our previous study that used the same proteomics platform, MMP-7 was found to be a sensitive biomarker during the first half of pregnancy for the detection of patients who subsequently developed late preeclampsia; herein, we showed that is also the case for early preeclampsia." (PMID 31163045, 2019). "Elevated MMP-7 early in gestation (8–22 weeks) and low PlGF later in gestation (after 22 weeks) are the strongest predictors for the subsequent development of late-onset preeclampsia, suggesting that the optimal identification of patients at risk may involve a two-step diagnostic process." (PMID 28738067, 2017).
preeclampsia (continued). "At this gestational-age interval, but unlike early preeclampsia with MVM that was predicted mostly by an increase in MMP-7, the prediction for severe early preeclampsia also involved the increase in gpIIbIIIa for 14% of the models trained on bootstrap samples of the original dataset." (PMID 31163045, 2019). "Although for the 8–16 and 16.1–22 weeks’ intervals when MMP-7 was selected as the best model in a majority of bootstrap trials, there were differences in the top proteins included for prediction of subsequent mild as opposed to severe late-onset preeclampsia." (PMID 28738067, 2017).
rectal cancer (3 papers, 2019 to 2023). A primary or metastatic malignant neoplasm that affects the rectum. "By analyzing the gene expression of CRC patients in the TCGA-COAD/READ- datasets, we found that the mRNA expression of MMP7 in colon and rectal cancer tissues was significantly higher than normal tissues." (PMID 37814323, 2023).
skin cancer (3 papers, 2016 to 2025). "MMP7 expression in keratinocytes is increased in pro-inflammatory conditions e. g. such as caused by tissue trauma resulting in acute and chronic wounds, autoimmune diseases such as lupus and by ultraviolet light in HaCaT cells and is also increased in skin carcinomas." (PMID 27078876, 2016). "As we know, there were some researches about the diagnostic value of autoantibodies against MMP-7 and Hsp70 in other cancers but not in skin cancers." (PMID 34336006, 2021). "MMP7, MMP11, and MMP14 play key roles in skin cancer progression." (PMID 40604111, 2025).
Trichiasis (3 papers, 2012 to 2018). Inversion and rubbing of the eyelashes against the globe of the eye. "This identified a variety of pro-inflammatory (IL1B, TNFA, S100A7, CXCL5, NOS2A) and tissue remodelling factors (MMP7, MMP9 and MMP12), which were associated with conjunctival scarring and trichiasis before surgery." (PMID 23285311, 2012). "In individuals with trachomatous scarring and/or trichiasis, factors involved in innate pro-inflammatory responses and matrix remodeling (IL1B, CXCL5, S100A7, CTGF, MMP7, and MMP9) were upregulated." (PMID 28966918, 2017). "MMP7 has consistently been found to be upregulated in scarring trachoma and trichiasis alongside MMP9 and MMP12 but there is less evidence for a role of MMP7 in active trachoma." (PMID 28966918, 2017).
urothelial carcinoma (3 papers, 2023 to 2025). A malignant neoplasm derived from the transitional epithelium of the urinary tract (urinary bladder, ureter, urethra, or renal pelvis). "MMP7 (Matrix Metalloproteinase 7) expression is a validated independent prognostic factor in urothelial carcinoma." (PMID 38782818, 2024). "In conclusion, in our cohort study combined with a systematic review and meta-analysis, we synthesized the results of our own and previously published independent data and validated pretreatment serum MMP-7 as a prognostic factor in urothelial carcinoma." (PMID 37175566, 2023). "Finally, we performed a systematic review and meta-analysis to provide a comprehensive overview of the clinical value of circulating MMP-7 levels in urothelial carcinoma." (PMID 37175566, 2023). "MMP7 participates in the signalling of the miR-133a-3p/SLC12A5/SOX18/MMP7 axis, which promotes the progression of urothelial carcinoma." (PMID 41228251, 2025). "A subgroup analysis of 593 patients with muscle-invasive high-grade urothelial carcinoma who underwent radical surgery (RC, RNU) or chemotherapy (CTX) showed that high pretreatment MMP-7 levels were significantly correlated with reduced OS (HR = 2.58; 95% CI = 2.04–3.26)." (PMID 37175566, 2023). "Based on them, currently available retrospective data sufficiently validate the use of the circulating pretreatment MMP-7 level as an independent prognostic factor in urothelial carcinoma, and therefore no further retrospective studies are needed." (PMID 37175566, 2023).
acute cystitis (2 papers, 2016 to 2021). An acute infection of the bladder. "Using IL-1β and MMP-7 as targets for immunotherapy, we succeeded in protecting susceptible Asc-/- mice against acute cystitis, confirming the potential of immunotherapy for this indication." (PMID 27732661, 2016). "The results confirm the importance of IL-1β and MMP-7 for the pathogenesis of acute cystitis and identify these molecules as functional targets for immunomodulatory therapy." (PMID 27732661, 2016). "We identify the cytokine Interleukin-1 beta (IL-1β) as a key immune response determinant in acute cystitis and successfully treat mice with severe acute cystitis by inhibiting IL-1β or the enzyme MMP-7 that processes IL-1β to its active form." (PMID 27732661, 2016). "Consistent with their intact inflammasome function, Mmp7-/- mice developed transient cystitis similar to C57BL/6 WT mice." (PMID 27732661, 2016). "In addition, all the patients with acute cystitis had positive MMP-7 levels, above the detection limit of 0.15 ng/ml." (PMID 27732661, 2016). "Finally, elevated levels of IL-1β and MMP-7 were detected in patients with acute cystitis, suggesting a potential role as biomarkers and immunotherapeutic targets." (PMID 27732661, 2016). "Finally, we detect elevated levels of these molecules in urine samples from patients with cystitis, suggesting clinical relevance and a potential role of IL-1β and MMP-7 both as therapeutic targets and as biomarkers of infection." (PMID 27732661, 2016). "To examine the human relevance of the findings in the murine UTI model, we collected urine samples from patients with acute cystitis or ABU and quantified the IL-1β and MMP-7 levels, by ELISA." (PMID 27732661, 2016). "The results show that patients with acute cystitis have more elevated concentrations of IL-1β and MMP-7 in urine, than patients with ABU, identifying IL-1β and MMP-7 as potential biomarkers of acute cystitis." (PMID 27732661, 2016). "Proteases inhibited by Batimastat other than MMP-7, were not transcriptionally regulated in any of the mice with acute cystitis or controls." (PMID 27732661, 2016).
acute myeloid leukemia (2 papers, 2022 to 2025). Acute myeloid leukemia (AML) is a group of neoplasms arising from precursor cells committed to the myeloid cell-line differentiation. "High expression of MMP7 was significantly associated with poorer overall survival (OS) in KIRC (P = 0.031), acute myeloid leukemia (LAML) (P = 0.00035), brain lower grade glioma (LGG) with P = 0.0086, and LIHC (P = 0.012)." (PMID 35785154, 2022). "In this study, MMP7 was highly expressed in acute myeloid leukemia (AML) and exhibited a significant correlation with adverse clinical outcomes." (PMID 40790216, 2025).
adenomyosis (2 papers, 2025). The growth of endometrial tissue inside the muscular wall of the uterine corpus. "MMP7 expression positively correlated with uterine volume in adenomyosis; MMP11 could be negatively associated with myometrial wall thickness ratio." (PMID 41272701, 2025). "Expression of key genes indicated enhanced ECM remodeling in adenomyosis, with MMP7, MMP9, and MMP11 emerging as potential discriminatory markers." (PMID 41272701, 2025). "We also found the expression of MMP7 to be inversely related to the uterine volume of adenomyosis patients." (PMID 41272701, 2025). "We found the expression of MMP7 to be significantly less in the eutopic endometrium of adenomyosis cases as compared to controls." (PMID 41272701, 2025). "Our transcriptomic analysis identified TNFAIP6, matrix metalloproteinase 7 (MMP7), TNFAIP3, leukemia inhibitory factor (LIF), and serum and glucocorticoid-regulated kinase 1 (SGK1) as the top 5 genes implicated in the inflammatory mechanisms of adenomyosis." (PMID 40989079, 2025). "Further, MMP7, MMP9, and MMP11 appear promising as clinically relevant discriminatory markers of adenomyosis." (PMID 41272701, 2025). "While MMP7 exhibited the highest expression in the co-existent group (p < 0.0001), MMP11 and IGFBP5 showed maximum expression in women with adenomyosis (p < 0.0001)." (PMID 41272701, 2025). "On comparing adenomyosis patients with controls, significant differences were observed in the expression of MMP9, MMP11, SERPINA1, IGFBP5, and TIMP1 (p < 0.05); however, MMP7 and THBS1 remained comparable." (PMID 41272701, 2025).
AIDS dementia (2 papers, 2017 to 2018). "In previous work, we have observed increased levels of MMP-7 in association with HIV dementia." (PMID 28302163, 2017). "We used 500 ng/ml MMP-7 as MMP levels in the nanogram per milliliter range have been detected in cerebrospinal fluid samples of patients with HIV dementia." (PMID 28302163, 2017).
aneurysm (2 papers, 2017 to 2022). Bulging or ballooning in an area of an artery secondary to arterial wall weakening. "Contrarily, the authors reported a significant increase in MMP-7 levels in patients diagnosed with large aneurysms and TAV and an increase in MMP-13 values in patients diagnosed with medium-sized aneurysms and TAV." (PMID 35563383, 2022). "Using a mouse model of aneurysm formation, we showed that the combination of Mmp-7 deletion and EC4-Fc overexpression significantly increased AAA severity." (PMID 29229950, 2017). "Although increased levels of apoptosis and proliferation have been previously shown in aneurysm samples, this study is the first to evidence that N-cadherin protein levels are significantly reduced, and MMP-7 activity is significantly increased in human aneurysmal tissue." (PMID 29229950, 2017). "Interestingly, combined deletion of Mmp-7 and overexpression of a soluble N-cadherin mimic EC4-Fc (a 50 kDa fragment) resulted in more severe aneurysms." (PMID 29229950, 2017).
bacterial pneumonia (2 papers, 2016 to 2024). Acute infection of the lung parenchyma caused by bacteria (e.g., Streptococcus pneumoniae, Haemophilus influenzae, Chlamydia pneumoniae, Mycoplasma pneumoniae, and Legionella pneumophila). "Additionally, we showed that MMP-7 and KL-6 could differentiate IPF patients from patients with bacterial pneumonia and healthy controls." (PMID 27293304, 2016). "Additionally, we showed that MMP-7 and KL-6 could clearly differentiate IPF patients from patients with bacterial pneumonia and healthy controls, suggesting their potential as diagnostic biomarkers." (PMID 27293304, 2016).
bone metastasis (2 papers, 2006 to 2021). Transfer of a neoplasm from its primary site to bones. "The level of MMP7 in patients with bone metastasis was much higher than that in patients without bone metastasis." (PMID 35069702, 2021).